HLA-G (major histocompatibility complex, class I, G)
Diseases named in the same sentence as HLA-G in open-access papers (continued):
Sharing a sentence is not in itself a finding about the gene and the disease.
infection (continued). "Higher pre-transplant sHLA-G levels were a risk factor for serious infection in HT.sHLA-G high levels are associated with less severe acute and chronic GvHD in allo HSCT.HLA-G 14-bp insertion/deletion polymorphism is associated with susceptibility to rejection in KT." (PMID 36311782, 2022). "MHC variants showed no important associations between class I antigen-presentation genes (HLA-A, HLA-B, and HLA-C) and nonclassical HLA class I genes (HLA-G, HLA-E, and HLA-F) in symptomatic infection susceptibility." (PMID 34650566, 2021). "Furthermore, HLA-G has been investigated with regards to preterm birth or intraamniotic inflammations/infections." (PMID 29540242, 2018). "The difference between these infections could be due to the production of proinflammatory cytokines which could induce interruption of HLA-G cycle more in human CMV infection than in malaria infection." (PMID 28166246, 2017). "In summary, these novel studies confirmed that upregulation of HLA-G expression and/or release is an immune escape mechanism performed by virus and bacteria during infection to avoid the recognition by immune effector cells and to reduce the inflammatory response." (PMID 27652273, 2016). "Finally, some authors have unraveled a role for HLA-G as a predictor of the response to treatments in patients with tumors or infections." (PMID 27652273, 2016). "As host immune defense mechanisms efficiently eliminate most infections, studies on HLA-G in infections are based on the rationale that this molecule decreases the efficacy of the immune response through wide-ranging effects on all cell types involved in the immune response." (PMID 24839609, 2014). "HLA-G levels are high early in infection and remain high in rapid progressors." (PMID 24839609, 2014). "Reported discrepancies in the results concerning HLA-G expression in hCMV or HIV infections may reflect differences in the models used or in infection status or stage between studies." (PMID 24839609, 2014). "For exemple, UTR-1 and UTR-3 have been associated with different levels of malaria infection under a recessive model, suggesting that HLA-G expression may have a predictive value for parasite infection outcome." (PMID 24376542, 2013). "Furthermore, the gp41 protein of the viral envelope upregulates the synthesis of IL-10 by monocytes; in turn this cytokine increases the expression of HLA-G molecules to control immune response and facilitate infection." (PMID 23841087, 2013). "The up-regulation of HLA-G in trophoblast cells by IL-10 at later stages of infection may enhance effects of inhibitory receptors expressed on decidual NK cells." (PMID 23418570, 2013). "However, there is evidence of up-regulation of HLA-G mRNA in response to transformation, neovascularization, inflammation, and infection." (PMID 22934097, 2012). "HLA-G can be a single marker of infectious diseases when dealing with pathogens and/or to the immune response, or it may constitute a therapeutic target, once its function has been clarified in particular types of infections." (PMID 35204759, 2022). "In addition, a number of studies have highlighted the important role of this immune checkpoint molecule in the modulation of the immune system in immune-related diseases, tumors, and infections through the structure and dynamics of the different HLA-G isoforms." (PMID 35204759, 2022). "Another clinical study found a correlation between high sHLA-G levels and improved disease outcome probably due to immune-dampening effects of HLA-G that suppress an excessive tissue-damage, possibly mediated by reduced neutrophil infiltration to the sites of infection." (PMID 35237271, 2022). "Overall, such information might open new avenues concerning the effect of some pathogens such as parasites in decreasing the expression level of HLA-G to restrict pathogenesis in some infections or to influence the immune responses after vaccination among others." (PMID 35204759, 2022).
infection (continued). "However, it is still unknown whether HLA-G plays a protective or pathologic role in maternal and fetal infections." (PMID 34685432, 2021). "Both forms of HLA-G may also play a role in maternal and fetal infections during pregnancy." (PMID 34685432, 2021). "Therefore, based on the major immunomodulatory roles of HLA-G both in infectious and non-communicable diseases, we hypothesize a more-than-likely plausible capacity of key infections to upregulate HLA-G as therapeutic or immunomodulatory options, potentially allowing us to manage other infections." (PMID 35204759, 2022). "Our study demonstrates that infection with both HHV-6A and HHV-6B induces the expression of HLA-G in infected ECs, possibly by induction of ATF3 expression, and this correlates with the inability to originate vascular-like structures in culture." (PMID 30523283, 2018). "Thus, HLA-G may be a single marker of infectious diseases, related to pathogens and/or to the immune response, or it may constitute a therapeutic target, once its function has been clarified in particular types of infections." (PMID 24839609, 2014). "High levels of HLA-G molecules are also found in the monocytes of untreated HIV-positive patients, possibly due to the pathogenesis of infection." (PMID 24839609, 2014). "The nonclassical human leukocyte antigen G (HLA-G) was strongly downregulated during neisserial infection (Log2FC -4.27)." (PMID 38179419, 2023). "As the infection progresses, B cells react to the increased IFN-γ secretion by upregulating the expression HLA-G (e.g., HLA-G1 & HLA-G5), leading to decreases on CD85j, which in turn limits the production of IFN-γ by MAIT cells, maintaining homeostasis, and avoiding dysregulated host responses." (PMID 34659215, 2021). "Regardless of the infection status, increased HLA-G expression became apparent 3 h after exposure to PBMC and was sustained for at least 6 h." (PMID 34659215, 2021). "Regulators of HLA-G in pregnancy-related tissues were also identified, and the role of HLA-G in different pregnancy complications including PE, PTB, and maternal and fetal infections during pregnancy is summarized." (PMID 34685432, 2021). "Regardless of the infection status, B-LCLs increased HLA-G expression in function of the recombinant IFN-γ levels added." (PMID 34659215, 2021). "Notably, SSc patients who were both HHV-6A/B and HLA-G positive, also displayed the highest titer of anti-U94 antibodies (p < 0.05), supporting a possible role of HHV-6A/B infection in the disease progression." (PMID 31878218, 2019). "Nasal polyps with HPV11 infection have shown HLA-G expression on epithelial cells, while no HLA-G expression has been observed in HPV negative polyps." (PMID 25477881, 2014). "Interestingly, where there was no infection, the levels of soluble HLA-G among patients who recovered from SARS-CoV-2 and those in the control group were not significantly different, even when grouped by their genotype (Ins/Ins, Ins/Del, and Del/Del)." (PMID 37342325, 2023). "The role of HLA-G on HPV mono-infection has not been completely elucidated yet." (PMID 30278059, 2018). "They hypothesized that the high expression of HLA-G was an indirect induction by infection of HIV-1, related to the pathogenesis of the infection, considering that HLA-G expression occurs in a very high proportion of monocytes, which are unlikely to be infected." (PMID 23841087, 2013).
infectious disease (12 papers, 2014 to 2025). A disorder directly resulting from the presence and activity of a microbial, viral, or parasitic agent in humans. "HLA-G variants and plasma levels of the molecule have been investigated in autoimmune and infectious diseases." (PMID 39081501, 2024). "The correlation of HLA-G with infectious diseases caused by viruses, bacteria, and protozoan parasites." (PMID 35204759, 2022). "Overall, HLA-G expression is upregulated in infectious diseases in response to changes in the cytokine microenvironment that is mainly related to increased levels of IL-10 and class I interferons." (PMID 35204759, 2022). "Aspects expected to be explored include (a) HLA-G expression is reported to be correlated with the progression of various infectious diseases." (PMID 34938296, 2021). "HLA-G modulates host immune response via interactions with its inhibitory receptors that are expressed on the surface of NK cells, T and B lymphocytes, monocytes, dendritic cells and neutrophils, and could thus play a role in susceptibility to infectious diseases." (PMID 25115633, 2014). "HLA-G expression is induced in pregnancy and some autoimmune, malignant, and infectious diseases." (PMID 35625671, 2022). "These different treatments received during pregnancy may also have modulated HLA-G expression due to the reduction of exposure to infectious diseases." (PMID 31235762, 2019). "Moreover, we propose the possibility of new solutions to cope with various infectious diseases based on the factors in NAbs-containing EVs, especially not causing unnecessary immune reaction due to HLA-G." (PMID 35002513, 2022). "Human leukocyte antigen-G (HLA-G), a polymorphic non-classical HLA (HLA-Ib) with immune-regulatory properties in infectious diseases." (PMID 40636371, 2025).
hematological malignancies (9 papers, 2014 to 2026). "In this review, we summarize current knowledge regarding HLA-G expression, genetic polymorphisms, and immunoregulatory mechanisms in hematological malignancies, highlighting their clinical and translational implications." (PMID 42083155, 2026). "High plasma HLA-G (sHLA-G) levels have been associated with immunosuppression and worse prognosis in several hematological malignancies, such as acute and chronic leukemias, Hodgkin’s lymphoma, and diffuse large B-cell lymphoma." (PMID 35774498, 2022). "Since it is important to understand the significance of HLA-G expression in hematological malignancies, we investigated the association of HLA-G 3′-UTR polymorphisms with event-free survival (EFS) in pediatric HL patients." (PMID 29285306, 2017). "More broadly, HLA-G expression in solid tumors has been consistently associated with suppression of NK and CTL activity, while in some hematological malignancies, paradoxically, HLA-G has been reported to reduce malignant B cell proliferation." (PMID 41445738, 2025). "The pathophysiologic HLA-G expression in solid und hematopoietic diseases is an important immune evasion strategy of tumors and linked to a certain composition of the TIL." (PMID 32993793, 2020). "In this regard, more clinical and basic studies are now required to establish a clear significance of HLA-G expression in hematological malignancies." (PMID 24800261, 2014). "Correlation between HLA-G expression and clinical outcome in hematological malignancies is unclear." (PMID 29285306, 2017). "Human leukocyte antigen G (HLA-G) is a nonclassical major histocompatibility complex class I molecule whose increased expression has been consistently associated with unfavorable prognosis in solid tumors and has emerged as a potential immunotherapeutic target in hematological malignancies." (PMID 42083155, 2026). "However, no clear correlation was established between HLA-G and unfavorable clinical outcome in hematological malignancies." (PMID 24800261, 2014).
adenocarcinoma (5 papers, 2008 to 2024). A common cancer characterized by the presence of malignant glandular cells. "Moreover, further analysis revealed a positive correlation between PD‐L1 and HLA‐G expression levels in patient with adenocarcinoma (LUAD, R = 0.8188, p < 0.0001." (PMID 39234811, 2024).
immune dysfunction (5 papers, 2016 to 2025). "Thus, HLA-G upregulation might have a similar role in SARS-COV2 related immune dysfunction." (PMID 34578436, 2021).
inflammation (4 papers, 2013 to 2025). Aberrant reaction of the microcirculation characterized by movement of fluid and leukocytes from the blood into extravascular tissues. "Another important finding was the greater expression of HLA-G molecules in the plasma cells of patients with severe liver inflammation and serious clinical manifestations of AIH-1 (sHLA-G ≥ 50% and score ≥ ++, except for two patients)." (PMID 36311782, 2022). "On the contrary, no AIH-1 patients with mild hepatic inflammation had plasma cells characterized by the presence of cytoplasmic and/or membrane HLA-G molecules." (PMID 36311782, 2022).
inflammatory myopathies (2 papers, 2010 to 2020). "As these cytokines are known to induce HLA expression in many cell types, it seems likely that HLA-G expression, seen in inflammatory myopathies, at least in part, results from stimulation by locally produced cytokines after injury." (PMID 32997665, 2020). "Furthermore, HLA-G may have important roles in inflammatory skin conditions and myopathies." (PMID 20593013, 2010).
respiratory diseases (2 papers, 2018 to 2021). "This is in concordance with findings, that HLA-G is expressed by lung macrophages and dendritic cells in 25% of patients with nonmalignant respiratory diseases." (PMID 29587858, 2018).
neurodevelopmental disorder (1 paper, 2023). A behavioral and cognitive disorder with onset during the developmental period that involves impaired or aberrant development of intellectual, motor, or social functions. "In the attempt to shed further light on ASD-associated immune profiles, we analyzed HLA/KIR receptors, HLA-G genotypes, NK subsets, and NK function in ASD-MO comparing results to those obtained in mothers of children who did not develop neurodevelopmental disorders." (PMID 37545517, 2023).
HLA-G also shares sentences with these, for which no sentence is quoted: triple-negative breast carcinoma (6 papers); juvenile idiopathic arthritis (5); intrauterine growth restriction (4); pancreatic ductal adenocarcinoma (4); systemic sclerosis (4); type 2 diabetes (4); brain tumors (3); breast (3); cystic fibrosis (3); lung adenocarcinoma (3); non-Hodgkin lymphoma (3); pancreatic adenocarcinoma (3); acute graft versus host disease (2); atopic asthma (2); bacterial infections (2); benign tumor (2); Bronchiolitis Obliterans (2); chronic hepatitis B (2); dementia (2); gastroesophageal reflux (2); gastrointestinal disease (2); Hypertension (2); Kawasaki disease (2); leukoplakia (2); scleroderma (2); serous carcinoma (2); Thrombocytopenia (2); acute coronary syndrome (1); acute leukemia (1); adenoid cystic carcinoma (1).
A further 101 diseases each share a sentence with HLA-G in 1 paper.